MMP2 (matrix metallopeptidase 2)
Diseases named in the same sentence as MMP2 in open-access papers (continued):
Sharing a sentence is not in itself a finding about the gene and the disease.
keloid (16 papers, 2008 to 2024). An irregularly shaped, elevated mark on the skin caused by deposits of excessive amounts of collagen during wound healing. "Since accumulating evidence has shown that gelatinases played a crucial role in the process of keloid formation, we summarized the current knowledge on the association between MMP-2 and MMP-9 expression and the pathological process of keloids through a comprehensive review." (PMID 39654616, 2024). "Inactivating mutations in MMP2 in humans lead to connective tissue underlying issues as seem in Torg–Winchester syndrome, multicentric osteolysis, arthritis syndrome, and possibly influence the formation of keloids." (PMID 29164121, 2017). "Up to date, only two eligible studies belonging to clinical researches implied the roles of MMP-2/MMP-9 on keloid formation." (PMID 39654616, 2024). "The researchers found that these drugs can alleviate keloids formation by elaborately regulating MMP-2 and MMP-9 expressions." (PMID 39654616, 2024). "Therefore, more future clinical studies are still warranted to better evaluate the association between MMP-2/MMP-9 and keloid formation." (PMID 39654616, 2024). "Thus, the pathway (MMP2 up-regulated by HIF1A) may be involved in the expansion of keloids and merit further experimental study." (PMID 18620599, 2008). "The reviewed studies demonstrate elevated expression levels of MMP-2 and MMP-9 in keloid tissue compared to normal skin, suggesting their pivotal role in driving the excessive collagen deposition and altered tissue architecture observed in keloids." (PMID 39654616, 2024). "Liposomes or polymeric nanoparticles can be designed to encapsulate anti-MMP2/9 drugs and deliver them directly to the fibroblasts or ECM in the keloid tissue." (PMID 39654616, 2024). "In summary, this review consolidates the current understanding of MMP-2 and MMP-9 in keloid pathogenesis, shedding light on their intricate involvement in the dysregulated keloids processes." (PMID 39654616, 2024). "Conversely, the upregulation of MMP-2 and MMP-9 have also been reported to inhibit keloid formation." (PMID 39654616, 2024). "In summary, this review consolidates our current understanding of MMP-2 and MMP-9 in keloid pathogenesis, shedding light on their intricate involvement in the dysregulated keloids processes." (PMID 39654616, 2024). "This comprehensive review extensively illustrates intricate roles of MMP-2 and MMP-9 in the regulation of keloids." (PMID 39654616, 2024). "Dysregulation of this balance not only underscores the significance of MMP-2 and MMP-9 but also opens new avenues for exploring targeted therapies for keloids." (PMID 39654616, 2024). "A previous pilot study demonstrated that the medians levels of both MMP-2 and MMP-9 were increased in the hypertrophic scar and keloid groups as compared to the donor skin." (PMID 39654616, 2024). "On the other hand, MMP-1, MMP-2, and TIMP1 were significantly upregulated in keloid fibroblasts by CM." (PMID 35083233, 2021). "The results demonstrated that keloid dermal fibroblasts exhibited significantly increased expression of MMP-1, MMP-2, and MMP-3 relative to normal or hypertrophic dermal fibroblasts." (PMID 33672186, 2021). "Elevated levels of MMP-2, TIMP-1, and TIMP-2 are observed in keloids, the imbalance of which appears to dysregulate collagen production and accumulation, with upregulated MMP-2 and MMP-9 expression additionally linked to cancer invasiveness." (PMID 31440236, 2019). "It meant, transcriptional levels of three array-up-regulated lncRNAs and three of their paired Wnt-genes, named CACNA1G-AS1/MMP2, HOXA11-AS/CDKN2A and LINC00312/KRT14, were significantly changed in keloids by intracellular qPCR measurement, simultaneously." (PMID 28404955, 2017). "dEl-k35/sLRP6E1E2-transduced keloid tissue explants had markedly reduced ECM components and MMP-2 and MMP-9." (PMID 29118355, 2017).
keloid (continued). "Specifically, MMP-2 and MMP-13 contribute extensively to break down types I and III collagens, the most abundant types of collagen in keloids and hypertrophic scars." (PMID 27339758, 2016). "Since both MMP-2 and MMP-9 have been found to be involved in the pathogenesis of keloids development, several potential drugs or substances that targeted the two genes are found to be effective on the treatments or preventions of keloids." (PMID 39654616, 2024). "On the other hand, by analyzing the expression patterns of MMP-2, MMP-9 in a patient’s keloid tissue, it may be possible to predict the response to different pharmacological interventions and tailor the treatment accordingly." (PMID 39654616, 2024). "Nevertheless, the present study revealed that developing more efficient drug delivery systems on MMP-2 and MMP-9 may be one of the successful treatments for managing keloids." (PMID 39654616, 2024). "In human patients, the level of MMP2 is significantly higher in collagen bundle regions of keloids compared to non-collagen bundle regions." (PMID 36983965, 2023). "Additionally, TGF-β1 increased the expressions and activities of MMP2 and MMP9 in keloid fibroblasts, which was suppressed by miR-21 inhibition." (PMID 27554193, 2016). "In a number of studies, there is a violation of the balance between matrix metalloproteinase-2 (MMP-2) and TIMP-2 in the development of diseases characterized by excessive tissue fibrosis (fibroproliferative alterations in the structure of the palmar aponeurosis, keloid scars)." (PMID 36136069, 2022). "However, the inhibitors of MMP-2 and MMP-9 for treating keloids are not yet available in human trials." (PMID 39654616, 2024).
Winchester syndrome (16 papers, 2007 to 2025). "Homozygous mutations in the SH3PXD2B and MMP14 genes cause Frank-Ter Haar syndrome and Winchester syndrome, respectively, whereas MMP2 gene mutation causes Torg and MONA syndromes." (PMID 41246610, 2025). "Multicentric Osteolysis Nodulosis and Arthropathy (MONA) is a rare skeletal disorder driven by mutations in the MMP2 gene, leading to bone and joint degradation." (PMID 39463871, 2024). "Inactivation mutation of MMP-2 causes Winchester Syndrome which is associated with arthropathy, osteoporosis, and even osteolysis of carpal and tarsal bones." (PMID 36393863, 2022). "A novel homozygous MMP2 mutation in a family with Winchester syndrome." (PMID 24894379, 2014). "At your suggestion, we conducted a new PubMed search and were able to find an article identifying a homozygous mutation in the catalytic domain of the MMP2 gene in two sisters with Winchester syndrome (Rouzier C1, Vanatka R, Bannwarth S, Philip N, Coussement A, Paquis-Flucklinger V, Lambert JC." (PMID 24894379, 2014). "As one example, a mutation at codon 404 in MMP2 causes Winchester syndrome." (PMID 17868464, 2007). "Another related disorder, Winchester syndrome (MIM# 277,950) is caused by variants of MMP14 but some of the patients have variants in MMP2." (PMID 37710205, 2023). "Torg-Winchester syndrome (TWS; OMIM #259600) is caused by a mutation in the gene encoding matrix metalloproteinase-2 (MMP2; OMIM *120360) located in 16q12.2." (PMID 24906390, 2014). "MMP2 variants were previously reported in NAO and Torg-Winchester syndrome." (PMID 37710205, 2023). "No previous reports described the simultaneous mutation of MMP2-Gen and 3-MCC deficiency in patients with Winchester syndrome." (PMID 21995273, 2011).
cardiomyopathy (15 papers, 2014 to 2025). A disease of the heart muscle or myocardium proper. "Dox-induced cardiomyopathy is also associated with increased levels of the MMP2- and 9, and pro-inflmammatory cytokines TNF-α, IL-1β, and IL-6 as similar to the results observed in kidney." (PMID 25742619, 2015). "In the present study, the development of cardiomyopathy in rats was indicated by elevated levels of CK-MB, cTn-I, MMP-2, AST, and LDH in the blood, recognized as key cardiac injury biomarkers." (PMID 40668529, 2025). "Ablation of a specific MMP can lead to compensatory effects, thus we next examined expression of Mmp3, which belongs to the stromelysin family, as well as examining MMP-10, Mmp2 and Mmp9, the two major MMP gelatinases that have been associated with DMD cardiomyopathy." (PMID 34947929, 2021). "In two studies performed on norepinephrine-induced cardiomyopathy and HF models in rats, it was found that RDN can inhibit transforming growth factor-β1, MMP2, collagen I, and inflammatory cytokines CRP and TNF-α." (PMID 36035484, 2022). "On the other hand, mice with genetic ablation of TSP2 had difficulty to cope with increased cardiac loading, with augmented matrix metalloproteinase (MMP)-2 and MMP-9 activities which disrupted myocardial matrix integrity, resulting in cardiomyopathy and fatal cardiac rupture." (PMID 36335340, 2022). "BNP, NTproBNP, troponin I, MMP-2, TIMP-1, and TIMP-2 levels rose with increasing severity stage but did not distinguish between Chagas cardiomyopathy and other cardiomyopathies." (PMID 25275382, 2014). "We showed significant elevations in BNP, NTproBNP, Troponin I, MMP-2, TIMP-1 and TIMP-2 among Tc+ individuals with cardiomyopathy compared to those without heart disease, findings consistent with previous studies." (PMID 25275382, 2014).
colorectal tumors (15 papers, 2001 to 2023). "On the other hand, MMP-2 and MMP-7 expression levels in the colorectal tumors were further increased by OPN deficiency." (PMID 28505114, 2017). "Levels of the MMP-2 gene expression in colorectal tumors were lower than in adjacent normal mucosa and significantly correlated with the depth of invasion, venous invasion, and presence of liver metastasis." (PMID 24395652, 2014). "In this study, we found a downregulation in MMP-2/9 expression following exposure to YQFS in rat colorectal tumors." (PMID 23506655, 2013). "MMP-2 mRNA was overexpressed in human colorectal tumours compared to normal colorectal tissue, which correlated with Dukes' stage and immunolocalized to the stromal compartment of the tumour tissue." (PMID 11401321, 2001). "Furthermore, increased expression of APOBEC3G in colorectal tumours has been found to promote hepatic metastasis through inhibition of miR-29 mediated suppression of matrix metalloproteinase 2 (MMP2)." (PMID 31547885, 2019). "Interestingly, PXN expression was positively correlated with Bcl-2, pBcl-2-S87, and MMP2 expression in colorectal tumors." (PMID 25826088, 2015). "The decrease of serum MMP-2 and TIMP-2 in more advanced tumor stages might be caused by the formation of MMP–TIMP complexes in colorectal tumor progression." (PMID 24395652, 2014). "Additionally, the cooperating expression of MMP2, 7 and 9 may induce colorectal tumour cells to invade locally and distantly or promote new blood vessel formation." (PMID 31937294, 2020). "Analysis of MMP2 and MMP9 mRNA expression levels in eight primary colorectal tumours revealed a 3.6–13.7-fold increase in MMP2 (p = 0.0356) and a 0.5–320.7-fold increase in MMP9 (p = 0.5286) levels compared with healthy colon tissue." (PMID 35954423, 2022). "Numerous studies have demonstrated increased MMP2 and MMP9 mRNA, protein, and/or activity in colorectal tumor specimens compared to the normal colonic mucosa." (PMID 34830271, 2021). "MMP2 and MMP9 mRNA, protein, and/or activity have been found increased in colorectal tumor specimens compared to normal colonic mucosa." (PMID 34830271, 2021). "Li and coworkers have shown that the imbalance between MMP-2 activity and its specific inhibitor TIMP-2 in colorectal tumor tissue might be a significant factor in the process of cancer invasion and metastasis." (PMID 24395652, 2014). "The active form of the MMP-2 enzyme was also present in the colorectal tumour tissue (7/8) but essentially absent in all normal colon samples examined (1/8)." (PMID 11401321, 2001). "MMP-3, MMP-9, MMP-13, MMP-2, and MMP-7 were upregulated in colorectal tumors in Min/OPN(+/+) compared to adjacent non-tumor parts." (PMID 28505114, 2017). "On the other hand, elevated expressions of MMP-2 and MMP-7 in colorectal tumors in Min mice were not lowered but rather increased by OPN deficiency in the present study." (PMID 28505114, 2017).
depression (15 papers, 2016 to 2025). "The expression of the MMP2 gene in the brain was associated with recurrence of depression." (PMID 33126421, 2020). "Finally, APOE, CSTD and MMP2 that varied genetically and in mRNA level of abundance were reported to be associated with depression." (PMID 33126421, 2020). "Increased MMP-9 levels, and to a lesser extent decreased MMP-2 levels, were documented in the depression group." (PMID 35370878, 2022). "Our study pointed out the effect of EZH2 in neuroinflammation and microglia activation of depression with the participation of the miR-29b-3p/MMP2 axis." (PMID 35172677, 2022). "We explored and adjusted for relevant variables previously linked to CVD: MMP-2, MMP-9, MMP-14, TIMPS, galectin-3, CRP, metabolic variables, life style variables, depression, and thyroid disease." (PMID 34702365, 2021). "Collectively, we made a hypothesis that EZH2 may influence neuroinflammation and microglia activation in depression via the regulation of miR-29b-3p/MMP2 axis." (PMID 35172677, 2022). "In conclusion, our data supported that EZH2 targeted miR-29b-3p expression by promoting H3K27me3 level to elevate MMP2 transcription and trigger microglia M1-type polarization, so as to exacerbate depression-like behaviors and neuroinflammation in depression rats." (PMID 35172677, 2022). "Furthermore, MMP2 functioned as a valuable biomarker and a possible reason for depression as it was consistently overexpressed in depression." (PMID 35172677, 2022). "For all measured MMPs (MMP-9, MMP-2, MMP-7) and TIMP-2 in blood, increased gene expression was statistically more significant at the mRNA level in patients with depression as compared to control individuals." (PMID 35370878, 2022). "Some studies showed that MMP-2 and MMP-9 genes had relative lower expression on both mRNA and protein levels in depression." (PMID 36045654, 2022). "It was also reported that the expression of MMP2 and MMP9 (mRNA and protein concentration) differs in people with recurrent depressive disorders and impaired cognitive functions compared to healthy controls." (PMID 33396569, 2020). "In relation to the cognitive phenotype we observe at the long-term, it is of interest that MMP-2 and MMP-9 activity are downregulated in serum of patients with recurrent depression, where higher MMP-levels were correlated with better cognitive performance." (PMID 33057053, 2020). "We have not explored the expression of miR-29a-3p and miR-29c-3p in depression, nor have we explored that the expression changes of miR-29a-3p and miR-29c-3p can affect the transcription level of MMP2." (PMID 35172677, 2022). "MMP2 and MMP9 were targeted by hsa-miR-451a, which was decreased by depression in AD patients." (PMID 36040555, 2022). "Interestingly, transcript and protein levels of MMP-2, MMP-9 and TIMP-2 were found to be downregulated in patients with the recurrent depressive disorder as compared to healthy individuals." (PMID 31172215, 2019). "Moreover, reduced mRNA and protein levels of MMP-2, MMP-9 and TIMP-2 were observed in patients diagnosed with depression and displaying lower performance in cognitive tasks, as compared to healthy subjects." (PMID 31172215, 2019).
glomerulosclerosis (15 papers, 2012 to 2024). A hardening of the kidney glomerulus caused by scarring of the blood vessels. "MMP-2 is a significant factor which is responsible for glomerulosclerosis development because mesangial cells with high expression of MMP-2 have greater proliferative abilities." (PMID 36359366, 2022). "Overexpression of MMP-2 results in structural changes in the tubular basement membrane and can generate all of the common features of kidney disease, especially glomerulosclerosis and interstitial fibrosis." (PMID 34402375, 2021). "These mice mimic human CKD, including tubular atrophy, glomerulosclerosis, and tubulointerstitial fibrosis, thus suggesting a role of MMP2 in CKD." (PMID 29464020, 2018). "It has been shown that decreased glomerular MMP-2 activity is associated with increased mesangial ECM accumulation and glomerular sclerosis in DN." (PMID 25143788, 2014). "Recently, histone H3K9 β-hydroxybutyrylation (H3K9bhb) upregulates matrix metalloproteinase-2 (MMP-2) to antagonize glomerulosclerosis in diabetic rat; H3K9bhb ameliorates aortic endothelial injury by promoting the generation of vascular endothelial growth factor (VEGF) in diabetic rats." (PMID 35909658, 2022). "Increased tissue mRNA expression and urinary protein levels of MMP-2 were observed in glomerular damage in renal transplant rejection, FSGS, and glomerulosclerosis models." (PMID 35834547, 2022). "Our previous studies distinctly showed that ATRA was able to increase the expression of MMP-2 and MMP-9, and reduce the expression of apoE, Col-IV, FN, and TGF-β1 in glomerulosclerosis rats." (PMID 23344030, 2012). "The expression of TIMP-1 was downregulated, while the mRNA and protein expression and activities of MMP-2 and MMP-9 were enhanced after treatment with benazapril and all-trans retinoic acid (ATRA) in Wistar rat model of glomerular sclerosis compared to normal group." (PMID 23057632, 2012). "In addition, transgenic renal proximal tubule-specific expression of the secreted, full length MMP-2 (FL-MMP-2) isoform is sufficient to induce all of the common features of progressive human renal disease, including glomerulosclerosis, tubular atrophy, interstitial fibrosis and inflammation." (PMID 28178341, 2017).